CCND1 (cyclin D1)
Diseases named in the same sentence as CCND1 in open-access papers (continued):
Sharing a sentence is not in itself a finding about the gene and the disease.
prostate carcinoma (339 papers, 2006 to 2025). A carcinoma that arises from epithelial cells of the prostate gland. "These factors highlight the importance of considering population-specific genetic and environmental influences when interpreting the role of the CCND1 rs9344 polymorphism in prostate cancer susceptibility." (PMID 40304827, 2025). "We evaluated CDK4 rs2069502, CDK6 rs2285332, CCND1 rs9344, p16INK4a rs11515, p15INK4b rs3217986, and RB rs3092904 polymorphisms using TaqMan® SNP Assays in a cohort comprising 532 prostate cancer patients and 567 control subjects." (PMID 40304827, 2025). "Several studies and one meta-analysis have reported the role of the CCND1 rs9344 polymorphism and the risk of prostate cancer." (PMID 40304827, 2025). "In our study, we observed a significant association between the GA genotype of the CCND1 rs9344 polymorphism and an increased risk of prostate cancer." (PMID 40304827, 2025). "Previous studies have revealed an association between the CCND1 rs9344 polymorphism and an increased risk of prostate cancer." (PMID 40304827, 2025). "In this Slovak case-control study, we identified an association between the GA genotype of the CCND1 rs9344 polymorphism and an increased risk of prostate cancer." (PMID 40304827, 2025). "We demonstrated an association between the CCND1 rs9344 GA genotype and prostate cancer risk in the Slovak population." (PMID 40304827, 2025). "We observed a significant association between the GA genotype of the CCND1 rs9344 polymorphism and an increased risk of prostate cancer (OR, 1.64; 95% CI, 1.23–2.20; p < 0.001)." (PMID 40304827, 2025). "Cyclin D1 and cyclin-dependent kinase 4 activity in G1-S-phase cell cycle transition is an important signalling axis in all cells, and increased Cyclin D1 expression/activity is associated with breast, colon and prostate cancers." (PMID 38958472, 2024). "Suppression of cell division cycle-associated 3 induced G0/G1-phase arrest to inhibit prostate cancer cell proliferation via cyclin D1 signaling inactivation and p21CIP1 accumulation." (PMID 35246013, 2022). "miR-193b: miR-193b conferred resistance to CDK4/6 inhibition via downregulation of the cyclin D1-encoding gene (CCND1) in prostate cancer." (PMID 34439268, 2021). "The purpose of our study was to investigate the associations between CCND1 and biochemical recurrence of prostate cancer (PCa)." (PMID 32566661, 2020). "An overexpression of cyclin D1 has been frequently associated with high-grade tumors such as breast tumors, colorectal tumors, prostate cancer, melanomas and lymphomas." (PMID 31583003, 2019). "Arctiin inhibits growth of the human prostate cancer PC-3 cells, which is associated with an arrest of cyclin D1 expression." (PMID 31362372, 2019). "The decrease of eIF-2α gene expression levels causes the cessation of cyclin D1 protein synthesis, which explains the basis of G1 phase arrest seen in prostate cancer cells during TA treatments." (PMID 29518944, 2018). "Hydroxytyrosol has also previously caused cell cycle arrest in prostate cancer cells by inhibiting cyclin-D1/E and CDK2/4 and inducing inhibitory p21/p27." (PMID 30004416, 2018). "In another study, α-chaconine inhibited prostate cancer cells proliferation (LNCaP and PC-3) by increasing p27 levels and downregulating Cyclin D1, and apoptosis in these cells was associated with caspase-dependent and independent pathways." (PMID 29799481, 2018). "It has also been associated with several anti-cancer mechanisms of action in prostate cancer including inhibition of complex 1, lipogenesis, decreases of cyclin D1, down-regulation of the insulin-like growth factor 1 receptor and AR downregulation." (PMID 28151974, 2017). "For instance, an elevated expression of cytoplasmic Ccnd1 has been detected by IHC in lymph node metastases originated from prostate cancer and is associated with poor survival." (PMID 27105504, 2016).
prostate carcinoma (continued). "Overexpression of cyclin D1 is associated with an oncogenic event in androgen-independent metastatic prostate cancer, suggesting a link of cyclin D1 expression to metastasis." (PMID 26840261, 2016). "For instance, cytoplasmic localization of Ccnd1 is observed in low-grade prostate carcinomas with reduced Ki-67 positivity whereas nuclear Ccnd1 is associated with high degree and elevated Ki-67." (PMID 27105504, 2016). "Numerous epidemiological studies have evaluated the association between the CCND1 A870G polymorphism and the risk of prostate cancer (PCa)." (PMID 25888980, 2015). "Although a number of studies have been performed to assess the association between the CCND1 A870G polymorphism and prostate cancer susceptibility, the conclusions have been inconsistent." (PMID 25888980, 2015). "To date, several studies have reported the role of the CCND1 G870A polymorphism in prostate cancer risk." (PMID 25888980, 2015). "In order to estimate the overall risk of the CCND1 G870A polymorphism associated with prostate cancer, we conducted a meta-analysis of results from ten case-control studies on the association of the CCND1 G870A polymorphism with PCa risk." (PMID 25888980, 2015). "In this study, we explored the ability of phenoxodiol to impact the cell cycle of prostate cancer cells and investigate the underlying signalling pathways c-Myc, Cyclin-D1, Ki-67 and p21WAF1." (PMID 25400509, 2014). "CCDC62 is linked to estrogen receptor transactivation, cyclin D1 expression in prostate cancer cells, and antibodies to this protein develop in a variety of cancers." (PMID 24312176, 2013). "For instance, overexpression of the potassium channel TREK-1, the androgen receptor, and cyclin D1 have each been implicated in increased proliferation in prostate cancer cells." (PMID 23990931, 2013). "As cyclin D1 deregulation is a hallmark of prostate cancer, the use of these two inhibitors can be envisaged in prostate tumors that exhibit altered cyclin D1 expression." (PMID 23667504, 2013). "The differential roles of cyclin D1 and the cyclin D1b splice variant in prostate cancer will be also be addressed, wherein divergent functions have been linked to altered proliferative control." (PMID 16863592, 2006). "Cyclin D1 associates with HDAC3 in prostate cancer cells, through a repressor domain motif that is required and sufficient for AR modulation." (PMID 16863592, 2006). "Also, in the context of prostate cancer, CCND1, a well‐established gene associated with prostate cancer susceptibility, was also identified." (PMID 39950845, 2025). "However, the GA genotype of CCND1 rs9344 polymorphism was significantly associated with an increased risk of prostate cancer (OR, 1.64; 95% CI, 1.23–2.20; p < 0.001)." (PMID 40304827, 2025). "Similarly, in prostate cancer, 18 eRNA‐linked genes associated with prostate cancer susceptibility displayed comparable or even higher levels of essentiality than the well‐known prostate cancer oncogene CCND1 (CCND1CERESscore = ‐1.20)." (PMID 39950845, 2025). "Silibinin has been reported to inhibit cell growth and induce G1 arrest in cell cycle progression of human prostate carcinoma, which was associated with decreased levels of cyclin D1, CDK4, and CDK6 and induction of Cip1/p21 and Kip1/p27, followed by increased binding with CDK2." (PMID 28030611, 2016). "MiR-15a and miR-16-1 have been identified as tumor suppressor genes in prostate cancer, and are associated with the expression gene that promote the survival, proliferation, and invasion in prostate cancer cells, including Bcl2, CCND1, and WNT3 A." (PMID 23130020, 2012). "Similarly, other reports have shown that TZDs lead to the degradation of cyclin D1 in prostate cancer, which causes cell cycle arrest, and a decrease in tumor cell proliferation." (PMID 21283708, 2011).
prostate carcinoma (continued). "Together, the data herein is the first to demonstrate that cyclin D1 can be differentially expressed in prostate cancer, and that the status and/or localisation of cyclin D1 expression are associated with meaningful changes in tumour marker expression and proliferative indices." (PMID 17375037, 2007). "Combined, these data suggest that cyclin D1 expression and localisation may influence proliferation and diagnostic factors in prostate cancer." (PMID 17375037, 2007). "Alternatively, prostate cancer cells may have invoked mechanisms to bypass the cyclin D1 requirement (e.g. RB loss), thereby weakening the necessity to induce cyclin D1 accumulation." (PMID 17375037, 2007). "And in another hormone-dependent cancer type, prostate cancer, overexpression of cyclin D1 is associated with a high proliferative index and a metastatic disease, and it has been suggested that high cyclin D1 may be related to the evolution of an androgen-independent disease form." (PMID 23336272, 2013). "In this study, we aimed to estimate the contribution of these selected polymorphisms (CDK4 rs2069502, CDK6 rs2285332, CCND1 rs9344, p16INK4a rs11515, p15INK4b rs3217986, RB rs3092904) within the cyclin D-CDK4/6-INK4-RB pathway to prostate cancer risk." (PMID 40304827, 2025). "Among genes uniquely downregulated by CBPD-409, we identified NKX3-1, CITED2 and CCND1, which are known for their critical roles in prostate cancer progression." (PMID 41044247, 2025). "Specifically, ISO suppresses cyclin D1 expression, thereby hindering cell cycle progression in prostate cancer cells." (PMID 40362444, 2025). "QRT-PCR analysis revealed lower expression of the β-catenin, Fzd8, Wnt5a and cyclin D1 genes in prostate cancer compared to benign prostatic hyperplasia tissues." (PMID 41465498, 2025). "This supports the utility of nano-formulations in enhancing anti-cancer efficacy, consistent with findings by Syrovets, Gschwend, who showed boswellic acid derivatives downregulating cyclin D1 in prostate cancer cells." (PMID 40284420, 2025). "To functionally assess the role of eRNA in tumor cells, we employed CRISPRi to suppress the enhancer activity of CCND1e in PC3 prostate cancer cells, which resulted in a marked decrease in the expression of both CCND1e and its target gene, CCND1." (PMID 39950845, 2025). "In prostate cancer, WWOX mediates G1 cell cycle arrest by downregulating cyclin D1 expression, which in turn suppresses the proliferation of 22Rv1 prostate cancer cells and inhibits tumor growth in nude mice." (PMID 41228229, 2025). "Some studies have focused on the prognostic value of cytoplasmic and/or nuclear CCND1 expression in prostate cancer, with the majority focusing on its nuclear localization." (PMID 40304827, 2025). "Aloe-emodin decreased the expression of β-catenin and the target genes cyclin D1 and c-Myc, causing pro-oxidant effects and elevated ROS, and it thus inhibited the growth of androgen-independent DU145 prostate cancer cells." (PMID 40427472, 2025). "The relative mRNA expression levels of CDK4, CDK6, CCND1, p16INK4a, p15INK4b, and RB were assessed in 44 prostate cancer tissues and 31 BPH tissues using qRT-PCR." (PMID 40304827, 2025). "Understanding the nuances of AR signaling is critical, particularly regarding how the modulation of Cyclin D1 and Bcl-2 contributes to prostate cancer development and progression." (PMID 40008000, 2025). "Amongst genes uniquely down-regulated by CBPD-409 versus reader bromodomain inhibitors, we identified NKX3–1, CITED2, and CCND1 that are known for their driver roles in prostate cancer progression." (PMID 38586029, 2024). "Cell cycle inhibition was previously reported in human prostate cancer cells, and the possible mechanism was the downregulation of cyclin D1 expression and the overexpression of cell cycle inhibitors as p21 and p27." (PMID 37298413, 2023).
prostate carcinoma (continued). "Phosphorylation of PXN activated ERK/ELK1 and increased the transcription of c-FOS and cyclin D1, which in turn facilitated the proliferation of prostate cancer cells." (PMID 36923874, 2023). "Our findings indicate that DAX1 downregulated the expression of CCND1 in prostate cancer cell lines." (PMID 37504255, 2023). "FOXO factors were previously reported to negatively regulate WNT pathway targets such as CCND1 in pancreatic and prostate cancers as well as osteosarcoma." (PMID 37584250, 2023). "In vitro, berberine has been found to significantly decrease the expression of cyclin D1, D2, and E in DU145 human prostate cancer cells, with the most pronounced effect on cyclin D1." (PMID 35699421, 2022). "We examined the frequencies of CCND1 and MDM2 copy number gains in cases with CDK12 mutations in the public data on advanced prostate cancer and found these to be 50% and 23%, respectively, which is generally consistent with our data." (PMID 36271301, 2022). "Such conclusions are further strengthened by reports assessing the ability of 5-aza to decrease β-catenin and cyclin D1 expression in endometrioid carcinoma and prostate cancer cells." (PMID 36120582, 2022). "We revealed that restoring FAM107A expression in prostate cancer cell lines such as DU 145 and PC 3 inhibited cell cycle progression, increased the proportion of cells in G1, and inhibited the expression of cyclin D1, a key protein in the G1 phase." (PMID 36010909, 2022). "In particular, Kauloniemi’s group demonstrated that miR-193b is hypermethylated in prostate cancer cells, leading to the upregulation of the target gene CCND1, which encodes for cyclin D1." (PMID 36498861, 2022). "Consistent with our reports, LOXL1‐AS1 sponges miR‐541‐3p by interacting with CCND1, thereby driving cell cycle progression and proliferation in prostate cancer." (PMID 34890108, 2022). "Knockdown of PSMC2 gave rise to the blocked development and metastasis of prostate cancer, which was probably resulted from regulating Akt/Cyclin D1/CDK6 signalling pathway." (PMID 33902600, 2021). "Downregulation of cyclin D1 and cyclin E1 has also been involved in the G2/M arrest of prostate cancer cell lines C4-2B and DU145 induced by resveratrol combined with docetaxel." (PMID 34513690, 2021). "Low miR-193b expression, thus CCND1 upregulation, rendered prostate cancer cells sensitive to treatment with palbociclib." (PMID 34439268, 2021). "In summary, CK increased cytotoxicity without hurting normal cells, sub G1 population, cleaved PARP and decreased the expression of pro-caspase-3, VEGF, TGF-β, IL-6, IL-10, Cyclin D1, c-Myc and Bcl-xL in prostate cancer cells." (PMID 34440920, 2021). "On the one hand, metformin induces cell cycle arrest in human prostate cancer cells through a decrease in Cyclin D1 expression and an upregulation of REDD1." (PMID 34570803, 2021). "Metformin has been demonstrated to downregulate cyclin D1 in various tumor cell lines, including stomach, colon, liver, breast, and prostate cancer lines." (PMID 34745255, 2021). "The activated MAPK pathway enhanced the interaction of EGR1 and cyclin D1, and then increased the cyclin D1 protein level in prostate cancer cells." (PMID 34681812, 2021). "Conversely, prostate cancer cells expressing high levels of miR-193b levels and low levels of CCND1 were resistant to the CDK4/6 inhibitor palbociclib." (PMID 34439268, 2021). "A recent study suggests that TMPRSS4 regulates both proliferation and invasion through Slug and cyclin D1 in prostate cancer cells." (PMID 33816264, 2021). "Further analysis of clinical samples identified CCND1 overexpression in the majority of cisplatin-resistant GCTs as well as its involvement in cisplatin resistance of ovarian and prostate cancer." (PMID 33923996, 2021). "Through downregulation of cyclin D1 expression and upregulation of p21, metformin, in breast, bladder, and prostate cancer cells, blocks the cell cycle in the G1 phase." (PMID 33350292, 2021).
prostate carcinoma (continued). "And it was also reported that LOXL1-AS1 expedited the development of prostate cancer through miR-541-3p and CCND1." (PMID 33726770, 2021). "This indicated the potential involvement of the Akt/Cyclin D1/CDK6 pathway in the PSMC2-induced proliferation of prostate cancer." (PMID 33902600, 2021). "For instance, an investigation exhibited that lncRNA LOXL1-AS1 downregulation inhibited prostate cancer progression through upregulating miR-541-3p and reducing CCND1." (PMID 33958701, 2021). "As expected, overexpression of Cyclin D1 successfully mitigated HNF1B‐mediated cell growth inhibition of DU145 prostate cancer cells." (PMID 33174391, 2020). "Proteins associated with cell survival such as cyclin D1 and PCNA were also induced more by M-TCM than TCM in all three prostate cancer cell lines." (PMID 32196489, 2020). "Recently, miR-487a-3p is found to function as a novel tumor repressor in prostate cancer by targeting cyclin D1 (CCND1)." (PMID 33520987, 2020). "For instance, miR-541 targeted the cell cycle regulator CCND1, which resulted in the inhibition of cell proliferation and progression of prostate cancer." (PMID 32709240, 2020). "LncRNA SNHG7 facilitates the proliferation and cycle progression of prostate cancer through miR-503/cyclin D1 axis." (PMID 32370736, 2020). "In serum, CNV in CCND1 was associated with MVI (p = 0.004); CNV in PTP4A, KRAS, ERBB2, TOP2A with positive STSM (p ≤ 0.035); CNV in CCND1 with the presence of incidental prostate cancer (p = 0.018)." (PMID 33298978, 2020). "All these data above indicate that HNF1B suppresses the proliferation of prostate cancer cells by inhibiting the expression of Cyclin D1." (PMID 33174391, 2020). "TGF‐β1 has been shown to inhibit Cyclin D1 in order to constrain prostate cancer growth and metastatic progression." (PMID 33174391, 2020). "In the present study, we demonstrate that HNF1B inhibits prostate cancer cell proliferation by suppressing Cyclin D1 expression." (PMID 33174391, 2020). "There are several studies focusing on the prognosis value of nuclear CCND1 in prostate cancer, while the studies have noticed the cytoplasmic CCND1 are very limited." (PMID 32566661, 2020). "In mechanism research, we determined that HNF1B inhibits prostate cancer cell proliferation by down‐regulating the expression of Cyclin D1." (PMID 33174391, 2020). "In prostate cancer, TGF‐β inhibits proliferation by prevention of G1 progression in early stages of prostate cancer cells via suppressing Cyclin D1 mRNA and protein expression." (PMID 33174391, 2020). "All these data together demonstrated that SMAD6 is a direct target of HNF1B in the regulation of Cyclin D1 expression and cell growth of prostate cancer cells." (PMID 33174391, 2020). "Cyclin D1 promotes cell proliferation and correlates with early cancer onset and tumour progression in many cancer types, including prostate cancer." (PMID 33174391, 2020). "Especially compound 9a, one of the artemisinin derivatives increases anti-proliferative, pro-apoptotic and anti-metastatic effect in PC-3 prostate cancer cells by decreasing the expression of Pin1, cyclin D1, c-Myc, elF4E, and PCNA." (PMID 32258027, 2020). "There is an article showing that through inhibition of CCND1 expression, miR-193a-3p increases the proportion of G1 prostate cancer cells, thus inhibits the cellular survival and proliferation." (PMID 32095323, 2020). "In prostate cancer AR target genes are suppressed by Cyclin D1, which limits, in such a way, the AR activity induced by its specific ligands." (PMID 33317149, 2020). "Then we did immunohistochemistry and found significant reverse correlation between HNF1B and Cyclin D1 protein levels in metastatic prostate cancer tissues." (PMID 33174391, 2020).